IGFBP7 (insulin like growth factor binding protein 7)
Diseases named in the same sentence as IGFBP7 in open-access papers (continued):
Sharing a sentence is not in itself a finding about the gene and the disease.
Sepsis (54 papers, 2013 to 2025). Sepsis is defined as life-threatening organ dysfunction caused by a dysregulated host response to infection. "TIMP-2 and IGFBP7 are produced and released by renal tubular cells in the early stages of injury caused by various injuries (such as sepsis, ischemia, and oxidative stress)." (PMID 37671089, 2023). "A comprehensive analysis was conducted to investigate the impact of senescence-related genes on sepsis, and 8 hub genes (IGFBP7, GMFG, IL10, IL18, ETS2, HGF, CD55, MMP9) associated with senescence were identified." (PMID 38259686, 2023). "Fifthly, although the urinary levels of IGFBP-7 and CysC were affected by sepsis; urinary IGFBP-7 and CysC were independently associated with increased risk for severe AKI, even after adjustment for the presence of sepsis." (PMID 29907141, 2018). "The fact that [TIMP-2]·[IGFBP7] are independently associated with AKI in sepsis is a relevant advantage of these biomarkers compared with more widely described NGAL or cystatin-C." (PMID 28884304, 2017). "In conclusion, we have validated the [TIMP-2]·[IGFBP7] test in an experimental model of sepsis-associated AKI using CLP." (PMID 27245788, 2016). "The product of the urinary concentrations of tissue inhibitor of metalloproteinases-2 (TIMP-2) and insulin-like growth factor-binding protein 7 (IGFBP7) has been validated for use in the early identification of sepsis-associated AKI and for risk stratification in this context." (PMID 32487237, 2020). "Variability in the timing of urine sampling may have affected urine [TIMP-2]*[IGFBP7] values, particularly as the time from kidney injury cannot be clearly determined in patients presenting with sepsis-associated AKI." (PMID 32487237, 2020). "Previous studies reported that urine [TIMP-2]*[IGFBP7] could be used for early diagnosis and risk prediction in sepsis-associated AKI." (PMID 32487237, 2020). "Urinary IGFBP-7 is increased in kidney damage caused by sepsis or ischemia." (PMID 32784748, 2020). "This study compared a three-level kidney-sparing sepsis bundle based on the KDIGO recommendations and guided by risk stratification using serial measurement of urinary [TIMP-2] x [IGFBP7] in patients with sepsis." (PMID 39279017, 2024). "A recent study showed that TIMP2*IGFBP7 is also an accurate predictor of the need for RRT in sepsis-induced AKI." (PMID 39596140, 2024). "In ALI, pulmonary tissue injury increases IGFBP7 secretion and exacerbates sepsis-induced ALI by activating the ERK1/2 pathway." (PMID 38840498, 2024). "In this study, we identified 8 senescence-related genes (IGFBP7, GMFG, IL10, IL18, ETS2, HGF, CD55, and MMP9) and developed a diagnostic model for the prediction of sepsis occurrence." (PMID 38259686, 2023). "Consensus cluster analysis we successfully classified sepsis patients into two distinct groups based on the expression of 8 hub genes (IGFBP7, GMFG, IL10, IL18, ETS2, HGF, CD55, and MMP9)." (PMID 38259686, 2023). "This review focuses on a number of kidney injury biomarkers, such as CysC, NAGAL, KIM-1, L-FABP, IL-18, suPAR, and [TIMP-2] • [IGFBP7], which have been widely studied in common clinical settings, such as sepsis, cardiac surgery, and contrast-induced AKI." (PMID 35930243, 2022). "The purpose of this study is to determine the role of urinary KIM-1, IL-18, and IGFBP-7 levels in predicting the occurrence of AKI in children with sepsis." (PMID 36545669, 2022). "There has never been a multicenter study in eastern Indonesia on KIM-1, IL-18, and IGFBP-7 in urine as biomarkers to predict the occurrence of AKI in children treated with sepsis in the pediatric intensive care unit (PICU) in Makassar, South Sulawesi." (PMID 36545669, 2022).
Sepsis (continued). "We also found IGFBP7 protein, a marker of acute kidney epithelial cell stress, was secreted into the tubular lumen in response to sepsis." (PMID 32034542, 2020). "Compared to the FDA approved AKI biomarker [TIMP2]*[IGFBP7], miR-452, especially urinary miR-452, showed high diagnostic efficiency for AKI in sepsis patients." (PMID 33204323, 2020). "However, when combined with plasma creatinine, TIMP-2 × IGFBP-7 showed potential to improve AKI prediction in sepsis patients presenting to the emergency department, as indicated by a significant result in the DeLong's test." (PMID 39811377, 2025). "Knockdown of IGFBP-7 effectively ameliorated the severity of renal injury in sepsis-induced AKI mice, as evidenced by reductions in urinary levels of creatinine, blood urea nitrogen, and albumin and attenuation of cell apoptosis through ERK1/2 signaling activation." (PMID 38788006, 2024). "The [TIMP-2] × [IGFBP-7] test could be useful in patients undergoing major surgery, who are hemodynamically unstable, or have sepsis." (PMID 39001241, 2024). "u[TIMP-2]*[IGFBP7], measured at time of septic AKI diagnosis, could not only be used as a tool assessing the risk of AKI progression in sepsis, but also provided additional prognostic information in hospital, such as subsequent death after AKI." (PMID 34906098, 2021). "We further evaluated the urinary [TIMP2]*[IGFBP7] in the sepsis patient cohort." (PMID 33204323, 2020). "Also of interest is that IGFBP7 is superior to TIMP-2 in surgical patients while TIMP-2 is best in sepsis-induced AKI." (PMID 23388612, 2013). "Furthermore, IGFBP-7 and TIMP-2 are closely associated with AKI induced by factors, such as cardiac surgery, kidney transplantation, decompensated heart failure, cardiac arrest, sepsis, and toxic nephropathy." (PMID 38788006, 2024). "Thus, we sought to evaluate the performance of [TIMP-2]·[IGFBP7] in an rat model of sepsis." (PMID 27245788, 2016). "Therefore, urinary TIMP-2 × IGFBP-7 examination may offer additional benefits regarding short-term mortality in the general population of patients visiting the ED, in contrast to patients with sepsis and a high incidence of AKI." (PMID 39811377, 2025). "Markers of cell-cycle arrest, such as TIMP-2 and IGFBP7, have been identified as potential predictors of sepsis-induced AKI, underscoring the importance of this mechanism in human sepsis." (PMID 40091836, 2025). "Another multicenter study conducted in ED included approximately half of the patients with sepsis; urinary TIMP-2 × IGFBP-7 improved the predictive power for both AKI and 30-day mortality." (PMID 39811377, 2025). "[TIMP-2]• [IGFBP7] exhibited predictive value for AKI with an AUC of 0.86 (95% CI 0.75-0.90) in stroke, 0.82 (95% CI 0.74-0.91) in sepsis, and 0.90 (95% CI 0.82-0.98) in post-cardiac surgery." (PMID 41071816, 2025). "Recent studies have introduced additional variables, such as Insulin-Like Growth Factor Binding Protein 7 (IGFBP7) and Tissue Inhibitor of Metalloproteinases (TIMP), as potential biomarkers for predicting AKI in patients with sepsis." (PMID 38561791, 2024). "IGFBP7 and TIMP-2 are proteins expressed in renal tubular cells during periods of cellular stress or injury, particularly in sepsis." (PMID 36545669, 2022). "In the setting of medical and non-sepsis patients, urinary NGAL had better predictive performance than urinary IL-18, urinary L-FABP, and urinary TIMP-2 × IGFBP-7: 0.3." (PMID 36371256, 2022). "Moreover, we first showed that adding u[TIMP-2]*[IGFBP7] to the clinical risk factor model, alone or combined with renal injury biomarkers, significantly improved the risk classification of AKI progression and AKI progression with death in sepsis, as evidenced by significant NRI and IDI." (PMID 34906098, 2021). "In this prospective study in patients with sepsis, we further directly compared the predictive performance of u[TIMP-2]*[IGFBP7] with the other novel injury/inflammation biomarkers in single or combination." (PMID 34906098, 2021).
Sepsis (continued). "U[TIMP-2]*[IGFBP7], uKIM-1 and uIL-18 predicted the progression of AKI in sepsis, with u[TIMP-2]*[IGFBP7] presented the greatest AUC (0.745, 95%CI 0.667-0.823) as compared to uKIM-1 (AUC 0.719, 95%CI 0.638-0.800) and uIL-18 (AUC 0.619, 95%CI 0.525-0.713)." (PMID 34906098, 2021). "u[TIMP-2]*[IGFBP7], measured at time of AKI diagnosis, predicted both AKI progression and AKI progression with death in the setting of sepsis." (PMID 34906098, 2021). "Currently, NephroCheck, based on urinary [TIMP2]*[IGFBP7], is the only FDA approved test for early detection of AKI, which has a relatively low sensitivity for sepsis patients." (PMID 33204323, 2020). "The sensitivity of urinary miR-452 for AKI detection in sepsis patients reached 87.23%, which was remarkably higher than the sensitivity of [TIMP2]*[IGFBP7] (61.54%) examined in the same cohort of sepsis patients." (PMID 33204323, 2020). "Urinary [TIMP2]*[IGFBP7] showed a sensitivity of 60% and a specificity of 85% for AKI diagnosis in the patients with sepsis, while urinary miR-376b had a sensitivity of 65% and a specificity of 85%." (PMID 33328388, 2020). "We compared the efficacies of urinary miR-376b and urinary [TIMP2]*[IGFBP7] in the diagnosis of patients with AKI and sepsis." (PMID 33328388, 2020). "Like procalcitonin in sepsis, the role of [TIMP-2]∙[IGFBP7] is to guide the clinician in a timely manner for further intervention of the patients at risk." (PMID 31712687, 2019). "The other markers already well studied in ICU patients or sepsis (e.g., KIM-1, IL-18, IGFBP-7, and TIMP-2) should be verified in the AP patients." (PMID 31366007, 2019). "In a CLP model of sepsis, the combination of TIMP-2 and IGFBP-7 has greater sensitivity in diagnosis of AKI compared with serum creatinine." (PMID 28430696, 2017). "Previous studies have reported that [TIMP-2]•[IGFBP7] (the product of TIMP-2 and IGFBP7) has shown significant predictive ability for the progression of AKI (stages 2–3) within 12 h of sample collection in patients with various diseases, including sepsis." (PMID 38702662, 2024). "The results showed that an increase in TIMP2*IGFBP7 4 h after the surgery is a reliable predictor of AKI (sensitivity, 83.9%; specificity, 73.8%), and an increase in MR-proADM is an indication of the potential occurrence and severity of postoperative sepsis." (PMID 39336978, 2024). "This difference might be explained by assuming that urinary IGFBP7 was superior to urinary TIMP-2 in surgical patients, while urinary TIMP-2 was best in sepsis-induced AKI." (PMID 35197070, 2022). "Nonetheless, the increase of urinary TIMP2 and IGFBP7 in AKI mainly depends on renal proximal tubule injury, raising the concern that mild tubular injury in septic AKI would reduce the sensitivity of [TIMP2]*[IGFBP7] in early AKI detection in sepsis patients." (PMID 33204323, 2020). "The sensitivity of urinary miR-452 for AKI detection in sepsis patients reached 87.23%, which was notably higher than the 61.54% achieved by urinary [TIMP2]*[IGFBP7], while the specificity of urinary miR-452 (78.00%) was slightly lower than that of [TIMP2]*[IGFBP7] (87.18%)." (PMID 33204323, 2020). "The mean values of urinary [TIMP2]*[IGFBP7] were significantly higher in the patients with sepsis and AKI than in those without AKI." (PMID 33328388, 2020). "Moreover, compared with urinary [TIMP2]*[IGFBP7], urinary miR-376b even showed a moderately higher sensitivity (65% vs. 60%) for detecting AKI in patients with sepsis." (PMID 33328388, 2020). "Especially, a significant portion of sepsis patients with AKI had urinary [TIMP2]*[IGFBP7] that was similar to that of sepsis patients without AKI, resulting in the failure of detecting AKI in these patients by using urinary [TIMP2]*[IGFBP7]." (PMID 33204323, 2020). "Sepsis patients with AKI had a significantly bigger value of urinary [TIMP2]*[IGFBP7] than the patients without AKI." (PMID 33204323, 2020).
Sepsis (continued). "Notably, compared to urinary [TIMP2]*[IGFBP7] or the FDA approved AKI biomarker, miR-452 showed a remarkable merit in the sensitivity of AKI detection in sepsis." (PMID 33204323, 2020). "Similar to LPS-induced AKI mice, there was a subset of sepsis patients with AKI whose [TIMP2]*[IGFBP7] values were no different from that of patients without AKI." (PMID 33204323, 2020). "In our study, urinary [TIMP-2]·[IGFBP7] was an early predictor of AKI in ICU patients regardless of sepsis." (PMID 28884304, 2017). "Taking into account the characteristics of our population, we conducted stepwise logistic regression analysis using as covariates age, sepsis, shock, previous hepatopathy, secondary ARDS, SAPS II, SOFA at admission and the worst value [TIMP-2]·[IGFBP7] for AKI and AKIN ≥ 2 prediction." (PMID 28884304, 2017). "In non-AKI patients, individual [TIMP-2]·[IGFBP7] levels were highest in trauma and sepsis patients." (PMID 25866432, 2015). "Combining u[TIMP-2]*[IGFBP7] with UACR could not further improve the performance both for predicting AKI progression or AKI progression with death in sepsis." (PMID 34906098, 2021). "The combination of [TIMP-2] × [IGFBP7] and PCT with cut-offs of 0.3 and 0.5, respectively, may help in stratifying the risk for AKI, regardless of sepsis." (PMID 32318859, 2020). "IGFBP-7 knockout can activate ERK1/2 signaling pathway, reduce creatinine, urea nitrogen, albumin, and cell apoptosis in mice urine, and effectively reduce the severity of renal injury, indicating that IGFBP-7 regulates AKI induced by sepsis through ERK1/2 signaling." (PMID 31661774, 2019). "In a mouse model of sepsis, TIMP-2 and IGFBP7 were shown to predict the development of AKI, with an area under the receiver operating characteristic curve (AUC) of 0.76 and 0.72, respectively; the result for the [TIMP-2]·[IGFBP7] complex was 0.89 (95% CI, 0.80–0.98)." (PMID 29854781, 2018). "[TIMP-2]·[IGFBP7] index values were dependent on the incidence of AKI but not of sepsis." (PMID 28884304, 2017). "Nevertheless, the sensitivity of TIMP-2 and IGFBP7 for diagnosing AKI in critically ill and sepsis patients remains as high as 0.87, and the negative likelihood ratio is 0.15 (95% CI: 0.04–0.64), indicating a considerable ability to rule out AKI." (PMID 41332898, 2025). "Known renal injury markers, such as markers Lcn2 (NGAL), Havcr1 (KIM1), Timp2, Igfbp7, are tubular injury markers and therefore are not indicative of the microvascular response in mouse CLP-sepsis." (PMID 40892345, 2025). "Following this logic, the Limiting AKI Progression in Sepsis trial was designed to evaluate the application of these bundles guided by serial measurements of TIMP-2 × IGFBP7 in patients with sepsis who did not have KDIGO stage 2 or 3 disease AKI at enrollment." (PMID 38462074, 2024). "To date, the influence of sepsis on TIMP-2 and IGFBP7 expression in critically ill patients is not well defined." (PMID 28884304, 2017). "Whereas neither TIMP-2 nor IGFBP7 was elevated in patients without AKI being unaffected by important co-morbidities such as chronic kidney disease, diabetes, and sepsis, patients with a [TIMP-2]*[IGFBP7] greater than 0.3 had seven times the risk for AKI." (PMID 26669781, 2015). "Univariate logistic regression analysis demonstrated significant associations between renal non-recovery and several factors, including age, sepsis severity, serum lactate level, SCr at enrollment, AKI stage, as well as urinary levels of [TIMP-2]•[IGFBP7] and CCL14 (all with P < 0.05)." (PMID 38702662, 2024). "Moreover, the correlation of sepsis with serum FGF23 (P = 0.068), urinary IGFBP-7 (P = 0.350), and urinary CysC (P = 0.391), however, did not remain significant after adjustment for age, body weight and illness severity in a multivariate analysis." (PMID 29907141, 2018).
Sepsis (continued). "Indeed, different performances of each component, such as observed in other settings, with TIMP-2 outperforming IGFBP-7 for sepsis-induced AKI diagnosis and IGFBP-7 being superior in the surgical setting, could not be evaluated." (PMID 30400873, 2018). "We observed no significant impact of sepsis on urinary TIMP-2, although the authors of a previous report presented a better prediction of AKI by the combination of TIMP-2 and insulin-like growth factor-binding protein-7 (IGFBP-7) in septic subjects than in post-surgery subjects." (PMID 25524453, 2014).